ATOH8 (atonal bHLH transcription factor 8)
Diseases named in the same sentence as ATOH8 in open-access papers (continued):
Sharing a sentence is not in itself a finding about the gene and the disease.
oligodendroglioma (2 papers, 2011 to 2022). A well-differentiated (WHO grade II), diffusely infiltrating neuroglial tumor, typically located in the cerebral hemispheres. "Besides, the level of ATOH8 expression increases in U2OS cells transfected with Cyclin-B1-EGFP fusion gene, and altered expression levels of ATOH8 are detected in human patients who suffer from oligodendrogliomas." (PMID 21857980, 2011).
colon cancer (1 paper, 2020). "Here, we confirmed that ATOH8 is associated with colon cancer hematogenous metastasis and poor prognosis in patients." (PMID 32000836, 2020).
colorectal tumours (1 paper, 2020). "Furthermore, we quantified ATOH8 expression levels in another cohort including 333 primary and 167 metastatic colorectal tumours, and ATOH8 was upregulated in metastatic CRC tissues (P < 0.0001, GSE131418)." (PMID 32000836, 2020).
deafness (1 paper, 2023). An inherited or acquired condition characterized by the complete loss of the ability to hear from one or both ears. "Our data showing that Atoh8 is differentially expressed in the TBCs during the postnatal period may provide clues to the basis of the deafness of unknown origin in Atoh8 mutant mice." (PMID 37339214, 2023).
depression (1 paper, 2022). "Meanwhile, the association of ATOH8 with depression or migraine has not been reported, and further studies are needed to delineate the possible mechanisms." (PMID 36704746, 2022).
iron deficiency (1 paper, 2014). "In contrast, hepatic Atoh8 and Hamp1 mRNA levels correlated in vivo in mice over a wide range of conditions of altered iron metabolism (iron overload, iron deficiency, hypotransferrinaemia, hypoxia, PHZ, EPO and carboplatin treatment)." (PMID 24236640, 2014).
iron overload (1 paper, 2014). "In addition we noted that Atoh8 mRNA was strongly down-regulated in liver expression microarrays of Tfrhpx/hpx mice, a mutant with a very high degree of liver iron overload, chronic anaemia and very low Hamp1 levels." (PMID 24236640, 2014).
muscular atrophy (1 paper, 2025). The loss of muscle tissue due to inactivity or disease. "Overall, we determined that the loss of Atoh8 leads to muscular atrophy." (PMID 41440013, 2025).
Parkinson disease (1 paper, 2025). A progressive degenerative disorder of the central nervous system characterized by loss of dopamine producing neurons in the substantia nigra and the presence of Lewy bodies in the substantia nigra and locus coeruleus. "In contrast, high expression of ATOH8 was closely related to the structure and function of ribosomes and Parkinson’s disease." (PMID 40282270, 2025).
teratoma (1 paper, 2022). A non-seminomatous germ cell tumor characterized by the presence of various tissues which correspond to the different germinal layers (endoderm, mesoderm, and ectoderm). "Atoh8 KD established iPS lines expressed similar Oct4, Sox2 and Nanog levels to controls and differentiated into three germ layers in teratoma." (PMID 36075976, 2022).
tumor (13 papers, 2016 to 2025). "Lower levels of Atoh8 have been associated with advanced tumor stage, metastasis, and poor survival." (PMID 41440013, 2025). "ATOH8, a transcription factor, is known to regulate cell differentiation and proliferation, and in this study, its expression appeared to suppress tumor progression by inhibiting cell migration and invasion." (PMID 40282270, 2025). "Atoh8 overexpression has been attributed to improved chemosensitivity and modulation of the tumor microenvironment." (PMID 41440013, 2025). "Suspended tumor cells with a CK8+/CD45−/DAPI+ phenotype actively responded to LSS by activating the expression of atonal bHLH transcription factor 8 (ATOH8), a fluid mechanosensor, with key roles in intravascular survival and metabolism plasticity." (PMID 35992829, 2022). "Injection into immunocompromised mice showed an increased growth of Atoh8 KD-derived tumours and a significant reduction in the overall survival of mice." (PMID 36075976, 2022). "Collectively, these data indicate that Atoh8 constrains cellular plasticity and the emergence of highly aggressive tumour cells." (PMID 36075976, 2022). "In tumor cells, the occupancy of active H3K4me3 of the Atoh8 promoter sequence was found to be replaced by a repressive H3K27me3 mark." (PMID 35053134, 2022). "ATOH8 expression among tumors is heterogeneous, and its role as a tumor suppressor or tumor promoter is still controversial." (PMID 35992829, 2022). "Lastly, overexpression of Atoh8 was also shown to reduce tumor formation and increase chemosensitivity in these cells." (PMID 35053134, 2022). "In this study, the authors identified the silencing of Atoh8 in tumor cells as an epigenetic mechanism induced by the tumorigenic LMP1 (Latent Membrane Protein-1)." (PMID 35053134, 2022). "Like many other bHLH transcription factors, so far, Atoh8 has also been observed to be involved in both embryonic development and carcinogenesis where it mainly acts as tumor suppressor." (PMID 35053134, 2022). "Using a mouse model of lung metastasis, we found that ATOH8 overexpression markedly increased tumour volume, tumour weight and metastatic foci in the lungs of nude mice, as expected." (PMID 32000836, 2020). "We then established mouse subcutaneous and metastatic tumour models and used serial sections, and immunohistochemical (IHC) staining to confirm ATOH8 upregulation in metastatic tumours in comparison with that in primary tumours." (PMID 32000836, 2020). "IHC staining of tumours indicated that ATOH8 and Ki-67 were upregulated upon ATOH8 overexpression, while cleaved caspase-3, an apoptotic marker, was downregulated." (PMID 32000836, 2020). "ATOH8 is such a shear stress sensor molecule, and its tumour-promoting effect in CRC still lacks strong evidence." (PMID 32000836, 2020). "The xenograft tumor model assays indicated the size of tumor mass derived from ATOH8 depletion cells were obviously larger than that derived from control cells." (PMID 27049918, 2016). "The xenograft tumor model assays indicated that ATOH8 restoration in CNE2 cells significantly inhibited the growth of the tumor mass." (PMID 27049918, 2016). "The results suggested that ATOH8 upregulation in CRC cells may happen during the “CTC stage” and be associated with tumour metastasis." (PMID 32000836, 2020). "Additionally, ATOH8 expression was further assessed in samples from clinical cohort 2 via WB, revealing that ATOH8 was markedly upregulated in tumour tissues relative to adjacent normal tissues (ANTs)." (PMID 32000836, 2020). "Besides, in previous researches, ATOH8 expression among tumours is heterogeneous, and its role as a tumour suppressor or tumour promoter is still controversial." (PMID 32000836, 2020). "However, the following study demonstrated that the expression of ATOH8 was significantly increased 3 fold after retinoic acid (RA) administration in GBM-derived stem-like tumor-initiating cells, suggesting the different function." (PMID 27049918, 2016).
tumor (continued). "In cancers, Atoh8 has often been observed to be downregulated in tumor tissues compared to either normal or adjacent non-tumoral tissues." (PMID 41440013, 2025). "Finally, we conducted external validation using The Cancer Genome Atlas (TCGA) database and further performed functional assays and drug sensitivity analyses on ATOH8 and DNASE2, additional tumor-specific markers identified by MR analysis." (PMID 40282270, 2025). "Up-regulation of ATOH8 promotes the intravascular survival of CRC cells in circulation, and a high expression of it predicts a poor clinical outcome in patients with CRC and contributes to tumor progression." (PMID 34113558, 2021). "More importantly, HK2 was also increased in tumour cells under LSS independent of ATOH8 overexpression." (PMID 32000836, 2020). "Our study presented a correlation between EMT markers and ATOH8, suggesting the novel emerging transcription factor ATOH8 appears to be a bona fide EMT regulator that is specifically suppressed by exogenous LMP1 to promote NPC tumor metastasis." (PMID 27049918, 2016). "Furthermore, ATOH8 has been found to bind with SMAD3, forming a transcriptional complex that activates the TGF-β signaling pathway, induces cellular senescence, and suppresses tumor transformation." (PMID 40282270, 2025). "RT-qPCR analysis revealed that the lncRNA levels of HDAC9, CMPK2, MINDY4B were up-regulated in the ALV-J induced tumor livers (positive group) compared to the normal livers in the negative group, whereas lncRNA levels of ATOH8 and LOC100859478 were down-regulated in the positive group." (PMID 35529873, 2022). "We further detected the expression of ATOH8 mRNA level and protein level in NPEC cell lines, NPC cell lines, non-tumor nasopharyngeal epithelial tissues and tumor nasopharyngeal epithelial tissues." (PMID 27049918, 2016).
cancer (11 papers, 2016 to 2025). A tumor composed of atypical neoplastic, often pleomorphic cells that invade other tissues. "The deletion of ATOH8 is one of the key mechanisms underlying the transition of SMAD3 from cancer suppression to cancer promotion." (PMID 37685308, 2023). "Given this new transcriptional variant, it would be interesting to see if the contradictory reports that are mentioned in the case of different cancers result from divergent functions of Atoh8 or because of the existence of more transcriptional variants." (PMID 35053134, 2022). "Here, we further explored whether the impairment of autophagy following either loss or downregulation of Atoh8 could explain any of the observed phenotypes during tissue development, differentiation, and cancer." (PMID 41440013, 2025). "The role of ATOH8 in different cancers, or even in different subtypes within the same cancer, is complex and multifaceted, making it an intriguing target for further investigation." (PMID 40282270, 2025). "Depletion of Atoh8 expression has been shown to correlate with advanced cancer stages and poor overall survival." (PMID 41440013, 2025). "Atoh8 depletion also increases the expression of cancer stem cell markers, such as OCT4, NANOG, and CD133." (PMID 41440013, 2025). "Recently, studies performed in cancer cells showed that inhibition of Atoh8 resulted in the downregulation of E-cadherin and upregulation of Vimentin bestowing mesenchymal phenotype to the cells." (PMID 31159500, 2019). "In recent years, Atoh8 has been further studied in other types of cancers." (PMID 35053134, 2022). "Given the ubiquitous expression and multiple regulatory roles of Atoh8 during embryonic development, it is not at all surprising to see its involvement in cancer and several other disorders." (PMID 35053134, 2022). "The expression of CRTAC1, DUSP2, ATOH8, and HIST2H2AC showed a significantly negative correlation with the activity of most hallmark-cancer pathways." (PMID 33604353, 2020). "However, another study released alongside showed that depletion of ATOH8 reprogramed non-cancer stem cells into cancer stem cells by directly releasing AFP, CD133, OCT4 and NANOG." (PMID 27049918, 2016).
infection (2 papers, 2021 to 2023). The state of being infected such as from the introduction of a foreign agent such as serum, vaccine, antigenic substance or organism. "This indicates that Atoh8 lox/VilCre mice with higher Gp2 expression also had functional characteristics during an infection." (PMID 34502262, 2021).
ATOH8 also shares sentences with these, for which no sentence is quoted: preeclampsia (2 papers); abdominal aortic aneurysm (1); autoimmune disease (1); esophageal cancer (1); haemochromatosis (1); Hyperglycemia (1); lung adenocarcinoma (1); metastatic colorectal cancer (1); migraine (1); neurodegenerative disease (1); non-small cell lung carcinoma (1); Osteopenia (1); ovarian carcinoma (1); parasitemia (1); thalassemia (1).